INS (insulin)
Diseases named in the same sentence as INS in open-access papers (continued):
Sharing a sentence is not in itself a finding about the gene and the disease.
viral hepatitis (11 papers, 2015 to 2025). An acute or chronic inflammation of the liver parenchyma caused by viruses. "Almost no previous epidemiological studies had a sample size large enough to investigate the independent association of HCC risk with insulin analogues after patients with chronic viral hepatitis had been excluded." (PMID 31200528, 2019). "There were significant multiplicative interactions between chronic viral hepatitis and premixed insulin analogues on risk of HCC after multiple adjustment (P = 0.010)." (PMID 31200528, 2019). "Similarly, the multivariate analysis from 2003 to 2013 showed any use of all insulin analogues to be positively associated with HCC occurrence only before exclusion of chronic viral hepatitis (adjusted OR, 1.20; 95% CI 1.03 to 1.40)." (PMID 31200528, 2019). "In the multiple conditional logistic regression analysis from 2003 to 2013, incident HCC risks were independently positively associated with any use of premixed insulin analogues (adjusted OR, 1.27; 95% CI 1.04 to 1.55) before exclusion of patients with chronic viral hepatitis." (PMID 31200528, 2019). "Patients only on insulin had a 5-fold odds of viral hepatitis (cOR 5.01; 95% CI: 0.92–31.56; p = 0.063)." (PMID 39977410, 2025). "Among 15 337 NHANES adults from 2 cycles with available data on diet, fasting insulin, C-peptide, and viral hepatitis, 199 individuals were anti-HCV positive and 41 individuals were HBV surface antigen positive." (PMID 36943385, 2023). "We recommend a closer liver surveillance among patients prescribed premixed insulin analogues with concomitant chronic viral hepatitis." (PMID 31200528, 2019). "More experimental research should explore the interplay between chronic viral hepatitis and different insulin analogues in HCC oncogenesis." (PMID 31200528, 2019). "In the univariate analysis from 2004 to 2013 after excluding participants with chronic viral hepatitis (952 HCC cases), the risk of incident HCC was still positively associated with use of insulin glargine and insulin detemir (OR, 1.49; 95% CI 1.06 to 2.10)." (PMID 31200528, 2019). "The significantly positive association between premixed insulin analogues and HCC occurrence diminished after exclusion of patients with chronic viral hepatitis." (PMID 31200528, 2019). "The addition of chronic viral hepatitis to any use of premixed insulin analogues further significantly increased the adjusted OR to 8.16 for HCC risk." (PMID 31200528, 2019). "We recommend closer liver surveillance for diabetic patients currently prescribed premixed insulin analogues with concomitant chronic viral hepatitis in general practice." (PMID 31200528, 2019). "We also observed a significant multiplicative interaction between chronic viral hepatitis and premixed insulin analogues on HCC risks (P = 0.010)." (PMID 31200528, 2019). "Nonetheless, there were no more independent positive associations between the incident HCC risks and any use premixed insulin analogues (adjusted OR, 1.35; 95% CI 0.92 to 1.98) after exclusion of patients with chronic viral hepatitis." (PMID 31200528, 2019). "Considering the first year of availability for each insulin analogue (2003 or 2004) and the presence of chronic viral hepatitis, there were four sets of study participants in our study." (PMID 31200528, 2019). "Our results showed a significant interaction between chronic viral hepatitis and premixed insulin analogues on risks of HCC." (PMID 31200528, 2019). "We have demonstrated the presence of additive and multiplicative interactions between chronic viral hepatitis and any use of premixed insulin analogues on HCC occurrence." (PMID 31200528, 2019). "There was limited information for us to perform additional stratified analysis to adjust for the influence of alcoholic consumption, viral hepatitis, smoking status, the degree of physical activity and fasting insulin levels." (PMID 25679378, 2015). "Viral hepatitis might also affect insulin function by downregulating GLUT-2 and -4." (PMID 36768699, 2023).
viral hepatitis (continued). "However, the association between HCC occurrence and premixed insulin analogues diminished among participants without chronic viral hepatitis (adjusted OR, 1.35; 95% CI 0.92 to 1.98)." (PMID 31200528, 2019). "Nevertheless, these studies did not further investigate whether the increased risk persisted among each class of insulin analogues, neither did they clarify the influence of chronic viral hepatitis." (PMID 31200528, 2019). "In the univariate analysis from 2003 to 2013 after excluding participants with chronic viral hepatitis (1237 HCC cases), HCC incidence was still positively related to any use of premixed insulin analogues (OR, 2.38; 95% CI 1.77 to 3.20)." (PMID 31200528, 2019). "Therefore, we aimed to test the hypothesis that chronic viral hepatitis might modify the reported associations between exogenous insulin analogues and HCC risks in a nationwide population with newly diagnosed diabetes on any antidiabetic agents, before and after excluding chronic viral hepatitis." (PMID 31200528, 2019). "When compared with participants who had neither chronic viral hepatitis nor any use of premixed insulin analogues, the sole presence of any use of premixed insulin analogues had a significantly higher adjusted OR of 1.51 for HCC occurrence." (PMID 31200528, 2019). "Nonetheless, most studies did not evaluate whether chronic viral hepatitis modifies the effects of insulin analogue on HCC." (PMID 31200528, 2019). "Actually, we intended to emphasize the intensified effect of chronic viral hepatitis on insulin analogues for HCC risks, rather than the independent role of each insulin analogue in HCC occurrence in the absence of chronic viral hepatitis." (PMID 31200528, 2019).
acute lymphoblastic leukemia (10 papers, 2013 to 2024). Leukemia with an acute onset, characterized by the presence of lymphoblasts in the bone marrow and the peripheral blood. "Insulin and insulin analogs are reported to be associated with a high proliferation rate and chemoresistance in patients with acute lymphoblastic leukemia." (PMID 28969062, 2017). "An increased risk of abnormal glucose tolerance and reduced insulin sensitivity were reported in acute lymphoblastic leukemia (ALL) survivors who received a TBI conditioning regimen before HSCT." (PMID 38473227, 2024). "In two participants, high insulin requirements were seen, although in one of these prior treatment for acute lymphoblastic leukaemia was an alternative explanation." (PMID 37562398, 2023). "After following the Group for Research on Adult Acute Lymphoblastic Leukemia (GRAALL) 2003 protocol that incorporates L-asparaginase (L-Asp) treatment, blood glucose levels became elevated for more than one year and insulin secretion was depleted." (PMID 36381756, 2022).
adrenal incidentalomas (10 papers, 2013 to 2026). "Subsequent in-depth, searches as topics and relationships were uncovered included topics specific to the pathology, radiology, etiology, and symptomatology of adrenal incidentalomas and insulin resistance as well as associated key pathophysiological interactions." (PMID 35457158, 2022). "There are key overlapping downstream effects of cortisol secreting adrenal incidentalomas that are hypothesized to underlie the reciprocal relationship between insulin resistance and adrenal incidentaloma." (PMID 35457158, 2022). "Although the majority of the research that would support this supposition has been performed on tissues other than adrenal tissue, the pathways presented provide a plausible means whereby insulin resistance may cause or play a role in the growth of adrenal incidentaloma." (PMID 35457158, 2022). "10% of the elderly population has an ‘adrenal incidentaloma’, up to 20% of these show low-grade autonomous cortisol secretion and 60% of patients with autonomous cortisol secretion have insulin resistance." (PMID 23577182, 2013). "Short-term GR antagonism is sufficient to reduce insulin resistance in some individuals with adrenal incidentalomas and mild cortisol excess." (PMID 23577182, 2013). "Nevertheless, in the literature, we can find some clinical evidence of improvements in insulin sensitivity after the resection of a non-functional adrenocortical adenoma." (PMID 37512046, 2023).
amenorrhea (10 papers, 2017 to 2024). The absence of menses in a woman who has achieved reproductive age. "Low insulin status is also linked to amenorrhea, related to hypothalamic sensors of insulin levels." (PMID 33042925, 2020). "Previous studies have shown decreased insulin, free T3, and leptin are associated with LEA and amenorrhea, while the results for free T4 and TSH are variable." (PMID 37342913, 2023). "The resumption of menses following lactational amenorrhea is preceded by a rapid increase in insulin levels due to peripheral insulin resistance that is thought to facilitate the resumption of ovarian function to pre-pregnancy levels." (PMID 31367382, 2019). "Therefore, elevated insulin levels as a result of insulin insensitivity could be adaptive if both earlier puberty and shorter lactational amenorrhea increase reproductive success." (PMID 31367382, 2019). "It was suggested that insulinresistance and high insulin levels, not amenorrhea oroligoamenorrhea, are responsible for the high level offerritin and iron, especially in obese women withPCOS." (PMID 37790203, 2023). "We attempted to test the efficacy metformin in a female patient with SHORT syndrome by measuring glucose and insulin during an extended Oral Glucose Tolerance Test (OGTT) in a 21-year old patient (BMI 17.5 kg/m2), who presented for endocrine assessment with a history of amenorrhoea." (PMID 31583022, 2019).
ankylosing spondylitis (10 papers, 2013 to 2025). An autoimmune chronic inflammatory disorder characterized by inflammation in the vertebral joints of the spine and sacroiliac joints. "In another series of non-diabetic and mostly non-obese patients with ankylosing spondylitis undergoing anti-TNF-α therapy, adiponectin concentrations related to insulin sensitivity and marginally to low BMI." (PMID 24286214, 2013).
Crohn disease (10 papers, 2013 to 2025). A gastrointestinal disorder characterized by chronic inflammation involving all layers of the intestinal wall, noncaseating granulomas affecting the intestinal wall and regional lymph nodes, and transmural fibrosis. "Rather the T1DM-Chrohn’s association is driven by different genes sharing common pathways such as CTLA4 and INS, or HLA-DRB1 with genes others than itself, which are genes of the HLA complex genes associated with both T1DM and Crohn’s disease." (PMID 31072055, 2019). "Interestingly, insulin levels were reported to be upregulated in patients with Crohn’s disease and ulcerative colitis." (PMID 40337860, 2025).
dermatitis (10 papers, 2014 to 2026). An inflammatory process affecting the skin. "Key findings indicated that elevated insulin levels and inflammatory markers correlate with the severity of these skin disorders." (PMID 41517578, 2026). "Skin disorders interfering with SC insulin administration (for example, inflammatory skin disease due to a type 3 immune complex reaction-Arthus reaction-localized)." (PMID 40995084, 2025). "Unexpectedly, a significant relationship between dermatitis and the levels of certain insulin-biosynthesis-and-secretion- or insulin-resistance-related polypeptides (GSTO1, FETUA, GSTP1, IGFALS or LDHA) was observed." (PMID 39062477, 2024). "These kind of skin disorders impair in some cases the insulin absorption, but as the skin structure is changed it might also change the tissue counter pressure and affect the way the drug is delivered by the injection device." (PMID 25122138, 2014). "Insulin therapy may lead to skin disorders, where the most common is lipohypertrophy, where extra adipose tissue is accumulated under the skin." (PMID 25122138, 2014).
diabetes insipidus (10 papers, 2010 to 2025). A disorder characterized by excretion of large amounts of urine, accompanied by excessive thirst. "In particular, copeptin concentrations 45 min after injection of insulin during an insulin tolerance test (ITT) provide the best sensitivity and specificity for detection of diabetes insipidus." (PMID 26578365, 2016).
gastroesophageal reflux disease (10 papers, 2012 to 2025). A chronic disorder characterized by reflux of the gastric and/or duodenal contents into the distal esophagus. "The most common potentially avoidable medications were medications for peptic ulcers and gastroesophageal reflux disease (30.5%), vitamins (14.6%), beta-blockers (9.8%), anticoagulants (7.9%), oral antidiabetics (5.4%) and insulin products (5.3%)." (PMID 38671427, 2024). "A 40-year-old African American male with a past medical history of type II diabetes on insulin, gastroesophageal reflux disease (GERD), and a BMI of 41 presented with a concern to remove multiple raised, nontender plaques on his anterior shins." (PMID 35720788, 2022).
generalized lipodystrophy (10 papers, 2015 to 2023). Almost complete absence of subcutaneous and/or visceral adipose tissue. "They included 65 patients with generalized lipodystrophy, 87 with partial lipodystrophy and 42 with defective insulin signaling, of whom 16 had a genetic INSR pathogenic variant, 25 had type B IR and 1 had a TBC1D4 defect." (PMID 33901270, 2021). "Of these, 185 (66%) had partial or generalized lipodystrophy (114 and 71 patients, respectively) and 65 (23%) had a primary disorder of insulin signaling, affecting the insulin receptor or components of the downstream insulin signaling cascade." (PMID 33901270, 2021). "MADB is characterized by brittle hair, mottled, atrophic skin, generalized lipodystrophy, insulin resistance, metabolic complications and skeletal features like stunted growth, mandibular and clavicular hypoplasia and acro-osteolysis of the distal phalanges." (PMID 31856865, 2019). "Recent reports have emphasized the concept that leptin has insulin-sensitizing effects, as it was demonstrated in patients affected with congenital generalized lipodystrophy and in mice treated with leptin sensitizers such as celastrol." (PMID 28626772, 2017). "Insulin sensitivity improved in all patients with generalized lipodystrophy except in patient #4, as measured by HOMA, plasma insulin level reduction, or lower insulin requirement." (PMID 25367549, 2015). "However, the mechanisms by which Metreleptin improves insulin sensitivity in Generalized Lipodystrophies (congenital and acquired) are still unclear." (PMID 38260129, 2023). "It is characterized by brittle or absent hair, mottled and atrophic skin, generalized lipodystrophy, insulin resistance, teeth abnormalities, metabolic complications and skeletal features like stunted growth, mandibular and clavicular hypoplasia and acro-osteolysis of the distal phalanges." (PMID 31856865, 2019).
Headache (10 papers, 2013 to 2025). Cephalgia, or pain sensed in various parts of the head, not confined to the area of distribution of any nerve. "Insulin may activate or sensitize meningeal nociceptors that may lead to enhanced headache susceptibility in persons with increased plasma insulin concentration." (PMID 35033025, 2022). "Relationship between enhanced insulin effect and migraine headache is further supported by the observation that hypoglycemia is a precipitating factor of migraine attacks." (PMID 35033025, 2022). "As for headache, DPP-4Is increased the risk of headache compared to insulin, TZD, and placebo (OR=1.22, 1.29 and 1.08, respectively)." (PMID 31788342, 2019). "Notably, the clinical improvements in headache severity appeared to correlate more closely with reductions in insulin levels than with changes in glucose, both under fasting and postprandial conditions." (PMID 40426647, 2025). "One experimental study published in 2017 found that the administration of insulin, glucagon, or leptin dramatically modulates the trigeminovascular system’s neuronal activity because of metabolic changes, which is a critical system in the pathogenesis of migraine headaches." (PMID 35627115, 2022). "For example, insulin-induced hypoglycaemia did not produce headaches in most migraineurs studied." (PMID 35627115, 2022).
irritable bowel syndrome (10 papers, 2018 to 2025). Irritable bowel syndrome (IBS) is a chronic functional condition of the lower gastrointestinal (GI) tract characterized by abdominal pain or discomfort and disordered bowel habit (diarrhea, constipation, or fluctuation between the two). "have been demonstrated to regulate levels of circulating insulin in pregnant women, and a reduced abundance has been associated with symptom severity in patients with irritable bowel syndrome." (PMID 33657123, 2021). "Many studies have shown the efficacy of FMT for treating diseases such as irritable bowel syndrome (IBS) and insulin sensitivity." (PMID 34158061, 2021).
Menstrual disorder (10 papers, 2017 to 2023). Category of disorders related to menstruation. "The treatment of PCOS mainly focuses on improving clinical symptoms, such as insulin sensitivity or menstrual disorder, through drug treatment." (PMID 35713297, 2022). "The study demonstrates a relationship between menstrual disorders and low levels of vitamin D, which may be related to AMH, insulin, and androgen or which could perhaps involve a yet-to-be-identified pathway." (PMID 30423869, 2018).
microcephaly (10 papers, 2012 to 2025). A congenital or acquired developmental disorder in which the circumference of the head is smaller than normal for the person's age and sex. "MOPD II is a rare syndrome of extreme intrauterine and postnatal growth retardation, microcephaly, resistance to growth hormone, severe insulin resistance, bone and dental dysplasia." (PMID 22693602, 2012).
Miscarriage (10 papers, 2017 to 2025). A pregnancy that ends at a stage in which the fetus is incapable of surviving on its own, defined as the spontaneous loss of a fetus before the 22th week of pregnancy. "This suggests that their apparent association with miscarriage risk may be mediated through or confounded by the core endocrine and metabolic disturbances captured by testosterone, insulin, and glucose." (PMID 41585786, 2025). "However, we do not believe that our prevalence of antidiabetic use would have been influenced by the inclusion of these women since neither insulin nor metformin (which represent almost all antidiabetic use in our cohort) have been associated with a higher risk of miscarriage." (PMID 37206113, 2023).
pancreatic adenocarcinoma (10 papers, 2008 to 2026). "For instance, a significant study has evaluated autoantibodies against insulin and beta-islet cells in pancreatic adenocarcinoma." (PMID 21209860, 2010). "As we observed that BLT1 is upregulated in islets adjacent to pancreatic adenocarcinoma, it is tempting to speculate that the tumours may induce additional paracrine growth stimulation by augmenting local insulin secretion in the pancreas." (PMID 18781173, 2008). "Furthermore, insulin levels and pancreatic function in relation to ENHO need to be tested in vivo and possibly in pancreatic adenocarcinoma patients." (PMID 40647442, 2025). "SHIP1 has been shown to be a promoter with higher activity than that of endogenous human insulin promoters and rat insulin promoters (RIP), which are used to direct expression in pancreatic adenocarcinoma that overexpresses pancreas and duodenal Homeobox gene 1 (PDX-1)." (PMID 33381459, 2020). "Additionally, an active role for NO/cGMP/cGKIα on MAPK phosphatase MKP-1 was previously reported in insulin-treated vascular smooth muscle cells, and another report showed that p42/p44 MAPK was a potential target of cGKI in pancreatic adenocarcinoma cells, thereby inducing cellular proliferation." (PMID 25978317, 2015).